LINC02888 (long independently transcribed non-coding RNA 2888)
Synonyms: KCCAT333
Gene: Long non-coding RNA gene on chromosome 7 (17,374,867 to 17,467,256, forward strand). Ensembl gene ENSG00000236318.
Diseases named in the same sentence as LINC02888 in open-access papers:
LINC02888 is named in the same sentence as 2 diseases in open-access papers, as found by Europe PMC text mining. Sharing a sentence is not in itself a finding about the gene and the disease.
LINC02888 shares sentences with these, for which no sentence is quoted: cervical cancer (1 paper); renal clear cell carcinoma (1).